FAM181A (family with sequence similarity 181 member A)
Synonyms: C14orf152
Tractability: No criterion of Open Targets' tractability assessment is met for any kind of drug.
Gene: Protein-coding gene on chromosome 14 (93,918,894 to 93,929,608, forward strand). Ensembl gene ENSG00000140067.
Subcellular location (Human Protein Atlas): Nucleoplasm; Cytosol
Gene Ontology:
Cellular component: cytoplasm
Genetic constraint (gnomAD): Loss-of-function variants: 7 observed, 16.92 expected, observed/expected ratio (o/e) 0.41, 90% interval 0.23 to 0.78. The upper end of that interval is the gene's LOEUF score, 0.78, which puts it in group 3 of 6, group 1 being the genes least tolerant of losing a copy. Missense variants: 349 observed, 388.79 expected, observed/expected ratio (o/e) 0.9, 90% interval 0.82 to 0.98. Synonymous variants: 183 observed, 169.19 expected, observed/expected ratio (o/e) 1.08, 90% interval 0.96 to 1.22.
Homologues: Orthologues: chimpanzee FAM181A (99% identical), macaque FAM181A (97% identical), dog FAM181A (87% identical), rabbit FAM181A (84% identical), mouse Fam181a (77% identical), rat Fam181a (77% identical), tropical clawed frog FAM181A (52% identical). Paralogues in human: FAM181B (24% identical).
Diseases named in the same sentence as FAM181A in open-access papers:
FAM181A is named in the same sentence as 6 diseases in open-access papers, as found by Europe PMC text mining. Sharing a sentence is not in itself a finding about the gene and the disease. The quoted sentences say what the papers report.
asthma (1 paper, 2015). "FAM181A was hypermethylated in peripheral blood from adults with asthma and in peripheral blood from infants exposed to asthma during pregnancy." (PMID 26074864, 2015).
colon adenoma (1 paper, 2013). An adenoma that arises from the colon. "Among these mutated genes, mutations in APC, FBXW7, KIAA1409, COL4A6, FAM181A, TFR2 and NRXN3 were previously reported in colon adenomas or adenocarcinomas." (PMID 23301059, 2013).
colon cancers (1 paper, 2013). "In addition, 5 other mutated genes were previously reported in colon cancers including FAM181A, NRXN3, KIAA1409, TFR2, and COL4A6." (PMID 23301059, 2013).
ovarian carcinoma (1 paper, 2019). A malignant neoplasm originating from the surface ovarian epithelium. "For RFS of patients with ovarian cancer, SPOCK2 and FAXDC2 were unfavorable prognostic biomarkers but ADAMDEC1, CCNA2, FAM181A, FOXA2, LRRTM1, NEIL3 and XPR1 were favorable prognostic biomarkers." (PMID 31794425, 2019). "High expression of GJB2, S100A2, SPOCK2, TGM1or EPS8 indicated a poor OS of patients with ovarian cancer, whereas ovarian cancer patients with higher expression of ADAMDEC1, CHEK1, EGFL6, FAM181A, FOXA2, LYPD1, PART1 or XPR1 possessed better OS." (PMID 31794425, 2019).
FAM181A also shares sentences with these, for which no sentence is quoted: adenocarcinoma (1 paper); colorectal adenoma (1).